OAZ1 (ornithine decarboxylase antizyme 1)
Description:
Ornithine decarboxylase (ODC) antizyme protein that negatively regulates ODC activity and intracellular polyamine biosynthesis and uptake in response to increased intracellular polyamine levels. Binds to ODC monomers, inhibiting the assembly of the functional ODC homodimer, and targets the monomers for ubiquitin-independent proteolytic destruction by the 26S proteasome. Triggers ODC degradation by inducing the exposure of a cryptic proteasome-interacting surface of ODC. Stabilizes AZIN2 by interfering with its ubiquitination. Also inhibits cellular uptake of polyamines by inactivating the polyamine uptake transporter. SMAD1/OAZ1/PSMB4 complex mediates the degradation of the CREBBP/EP300 repressor SNIP1. Involved in the translocation of AZIN2 from ER-Golgi intermediate compartment (ERGIC) to the cytosol.
Synonyms: AZ1; OAZ; AZI; MGC138338
Tractability: Small molecule: a high-quality ligand is known. PROTAC: ubiquitination databases record sites on it.
Gene: Protein-coding gene on chromosome 19 (2,269,509 to 2,273,492, forward strand). Ensembl gene ENSG00000104904.
Subcellular location (Human Protein Atlas): Vesicles; Centriolar satellite
Pathways (Reactome):
Metabolism: Metabolism of polyamines; Regulation of ornithine decarboxylase (ODC)
Gene Ontology:
Molecular function: ornithine decarboxylase inhibitor activity; protein binding
Biological process: positive regulation of protein catabolic process; polyamine biosynthetic process; positive regulation of intracellular protein transport; biogenic amine metabolic process; negative regulation of polyamine transmembrane transport
Cellular component: cytoplasm; cytosol; nucleus
Genetic constraint (gnomAD): Loss-of-function variants: 22 observed, 22.08 expected, observed/expected ratio (o/e) 1, 90% interval 0.71 to 1.42. The synonymous counts are far from expectation, so gnomAD's model fits this gene poorly and the ratio says little. Missense variants: 412 observed, 291.82 expected, observed/expected ratio (o/e) 1.41, 90% interval 1.3 to 1.53. Synonymous variants: 192 observed, 120.39 expected, observed/expected ratio (o/e) 1.59, 90% interval 1.42 to 1.8.
Homologues: Orthologues: chimpanzee OAZ1 (100% identical), macaque OAZ1 (99% identical), guinea pig OAZ1 (91% identical), mouse Oaz1 (84% identical), tropical clawed frog oaz1 (77% identical), pig OAZ1 (69% identical), dog OAZ1 (68% identical), zebrafish oaz1a (60% identical), rat Oaz1 (59% identical). Paralogues in human: OAZ2 (42% identical), OAZ3 (28% identical).
Diseases named in the same sentence as OAZ1 in open-access papers:
OAZ1 is named in the same sentence as 24 diseases in open-access papers, as found by Europe PMC text mining. Sharing a sentence is not in itself a finding about the gene and the disease. The quoted sentences say what the papers report.
oral cancer (7 papers, 2008 to 2025). "OAZ1 exhibits tumor inhibitory activity by affecting cell proliferation, apoptosis, and differentiation in oral cancer cell lines, leukemia, and non-small cell lung cancer." (PMID 40823069, 2025). "OAZ1 was reported to display tumor-suppressor activities through affecting the cell proliferation, apoptosis, and differentiation in oral cancer cell lines and leukemia." (PMID 31127087, 2019). "Inhibition of polyamine synthesis by ornithine decarboxylase antizyme-1 (OAZ) in human oral cancer cell line resulted in accumulation of decarboxylated S-adenosylmethionine (dcSAM), which acts as a competitive inhibitor of methylation reactions." (PMID 20838441, 2010). "Profiling of salivary mRNA indicated four major biomarkers of oral cancer including interleukin-1-β (IL1β), interleukin-8 (IL8), ornithine decarboxylase antizyme-1 (OAZ1) and spermidine/spermine N1-acetyltransferase (SAT)." (PMID 19424479, 2008). "Wang and Jiang found that OAZ1 overexpression resulted in the inhibition of cell proliferation and induction of cell differentiation through upregulating LOR, a differentiation biomarker, in human oral cancer cells." (PMID 31127087, 2019).
non-small cell lung carcinoma (4 papers, 2019 to 2025). A group of at least three distinct histological types of lung cancer, including non-small cell squamous cell carcinoma, adenocarcinoma, and large cell carcinoma. "OAZ1 was down-regulated in cisplatin-resistant non-small-cell lung cancer." (PMID 38397997, 2024). "Six of these genes (MUM1, AC016876.1, PLK5, HCN2, OAZ1, AC027307.2) have been identified as prognostic features for many cancers, such as colorectal cancer, breast cancer, non-small cell lung cancer." (PMID 36304471, 2022).
breast carcinoma (3 papers, 2017 to 2025). "Four high-risk independent prognostic factors (OAZ1, SRM, SMOX, and SMS) were validated as being upregulated in breast cancer tissues." (PMID 40823069, 2025). "On the contrary, OAZ1 overexpression suppressed ER mRNA expression in human breast cancer cells." (PMID 28362829, 2017).
colorectal cancer (2 papers, 2018 to 2022). A primary or metastatic malignant neoplasm that affects the colon or rectum. "A high level of ODC activity had been observed in the initial stage of colorectal cancer, and OAZ1, a type of tumour suppressor, can bind to ODC and facilitate its degradation." (PMID 29435126, 2018).
leukemia (2 papers, 2024 to 2025). A malignant (clonal) hematologic disorder, involving hematopoietic stem cells and characterized by the presence of primitive or atypical myeloid or lymphoid cells in the bone marrow and the blood. "Specifically, in leukemias, PTMA has been reported in fusion with OAZ1 and CXCR4." (PMID 38338888, 2024).
ovarian carcinoma (2 papers, 2017 to 2021). A malignant neoplasm originating from the surface ovarian epithelium. "We confirm the utility of all candidate reference genes and miRNAs but especially of OAZ1 and hsa-miR-6835-3p by measuring their expression abundance and stability in serum exosomes of an independent cohort of ovarian cancer patients and of healthy control individuals (n = 10 each group)." (PMID 33407103, 2021).
emphysema (1 paper, 2006). "Fifteen genes were thus found to be upregulated in fibroblasts of emphysema, among them IGFBP-rP1 (4.9-fold), LOX (3.3-fold), LOXL2 (3.9-fold) and TIMP3 (3.0-fold), whereas 121 genes were downregulated, among them CDK4 (6.3-fold), FOSL1 (4.8-fold), OAZ1 (6.7-fold) and IGFBP-5 (5.3-fold)." (PMID 16504044, 2006).
lung carcinoma (1 paper, 2019). "However, the role of OAZ1 in lung cancer, especially in drug resistance, and its regulation mechanism are still not known." (PMID 31127087, 2019). "Importantly, the opposite expression pattern (higher HDAC1 and lower OAZ1) correlated with bad treatment response and poor overall survival than other groups in lung cancer." (PMID 31127087, 2019).
multiple myeloma (1 paper, 2019). "We found that ZEB2-BCL11B (as also reported in the manuscript) and OAZ1-MAFK fusions were previously annotated in two AML and one multiple myeloma, respectively." (PMID 31817495, 2019).
oral squamous cell carcinoma (1 paper, 2024). "The up-regulation of the OAZ1 gene has been demonstrated in three studies in oral squamous cell carcinoma (OSCC) and chronic myeloid leukemia (CML)." (PMID 38397997, 2024).
osteosarcoma (1 paper, 2020). A usually aggressive malignant bone-forming mesenchymal neoplasm, predominantly affecting adolescents and young adults. "Next, we compared thetranscriptional stability of several normalizers that were formerly recommendedfor use in canine osteosarcoma without transcriptome-wide expression profiling forthis context such as OAZ1 or B2M,HNRNPH, RPS5 and RPS19." (PMID 32296879, 2020).
periodontal disease (1 paper, 2024). "The significantly low levels of OAZ1 and SAT1 reflect a unique trend of polyamine dysregulation in periodontal disease." (PMID 39408925, 2024).
periodontitis (1 paper, 2024). An acute or chronic inflammatory process that affects the tissues that surround and support the teeth. "This generates reservations for the reliability of OAZ1 and SAT1 as biomarkers for OSCC in patients with concomitant periodontitis and smoking habits." (PMID 39408925, 2024). "As OAZ1 serves to inhibit ODC, this may provide explanation for the increased ODC levels reported in periodontitis." (PMID 39408925, 2024). "Smoking also increased levels of OAZ1 and SAT1 in periodontitis." (PMID 39408925, 2024).
viral infection (1 paper, 2022). "Immunofluorescence microscopy confirmed that the reduced expression of OAZ1 significantly inhibited viral infection in the intestinal epithelium of viruliferous insects." (PMID 37676339, 2022). "Thus, during viral infection, the ability for OAZ1 to mediate the degradation of ODC1 is significantly inhibited, finally leading to the increase of ODC1 in the polyamine biosynthesis pathway." (PMID 37676339, 2022). "RT-qPCR and western blot assays showed that the mRNA and protein levels of OAZ1 and ODC1 were both upregulated during viral infection in insect vectors." (PMID 37676339, 2022). "Taken together, these results suggested that RSMV M competed with ODC1 to bind OAZ1, thereby releasing OAZ1 from its inhibiting the function of ODC1 during viral infection in insect vectors." (PMID 37676339, 2022).
cancer (15 papers, 2016 to 2025). A tumor composed of atypical neoplastic, often pleomorphic cells that invade other tissues. "Several reports have indicated that OAZ1 was associated with malignant behaviors, such as tumor growth, apoptosis, and differentiation in various cancer types." (PMID 31127087, 2019). "Ornithine decarboxylase antizyme (OAZ1 gene) is a potential therapeutic target in various malignant tumors because it plays relevant roles in cellular functions, including genomic stability, proliferation, differentiation, and apoptosis." (PMID 38397997, 2024). "OAZ1 is also present at high levels in the initial stages of cancer and can inhibit high levels of polyamine formation." (PMID 29435126, 2018). "IL8, SAT, DUSP1, IL1b, HA3, S100P, and OAZ1, which are related to cancer." (PMID 38522008, 2024). "One possible explanation was that the function of OAZ1 mediating ER transcription might vary between primary normal and cancer cells." (PMID 28362829, 2017). "The expression levels of OAZ1, SMOX, SRM, and SMS were significantly elevated in cancer tissues compared to normal tissues, as confirmed by qRT-PCR, Western blot, and immunohistochemistry." (PMID 40823069, 2025). "Seven reference genes (YWHAZ, GNAS, GAPDH, OAZ1, PTMA, B2M, and ACTB) were screened out among the 95 candidate reference genes from the data set of the platelets’ transcriptome of pan-cancer and 73 commonly known reference genes." (PMID 35770000, 2022). "All six pre-specified cancer genes (IL8, IL1, SAT, OAZ1, DUSP1 and S100P) were up-regulated in cancer versus control patients with from nearly twofold to over threefold higher levels (p<0.01 for all based on delta Cq values)." (PMID 27411053, 2016). "A small number of hypoxia-associated genes (APLN, HIF1A, and BNIP3), cancer stem cell (CSC) markers (CD24 and CD44), hormonal regulation (HR) genes (ESR1, PGR, and TFF1), other selected genes (PPARGC1A, ILK), and HKGs (RPL32, GUSB, TBP, OAZ1 and NONO) were also included in the panel." (PMID 34206049, 2021).
tumor (10 papers, 2016 to 2025). "Antizyme, particularly OAZ1, is known to suppress tumor growth by facilitating the degradation of ODC37." (PMID 40032914, 2025). "Signals for OAZ1 expression were detected rather constantly in the vast majority of tumor cells across all HS tested (mean 97.5%, range: 95.5–99.4%), arguing for generally sufficient and even accessibility of mRNA in all samples tested." (PMID 39619201, 2024). "OAZ1 was identified as the gene with the highest expression stability across samples and tumor types." (PMID 33407103, 2021). "The increase in HDAC activity would contribute to the epigenetic-mediated downregulation of OAZ1, a candidate tumor-suppressor gene, and thus results in drug resistance." (PMID 31127087, 2019). "Further, OAZ1 overexpression has been shown to have a tumor-suppressive effect in C57BL/6 and DBA/2 mice." (PMID 28362829, 2017). "Mechanistically, S11 could upregulate OAZ1, a candidate tumor-suppressor gene, through inhibiting HDAC activity." (PMID 31127087, 2019). "Furthermore, we also examined the Ac-H4 and OAZ-1 expression levels in tumor tissue samples from the four groups." (PMID 31127087, 2019). "Moreover, knocking down OAZ1 expression conferred the decrease in sensitivity to cisplatin and increase in cell migration capability in cisplatin-resistant NSCLC cells, indicating that OAZ1 plays a tumor-suppressor role in NSCLC." (PMID 31127087, 2019). "Our results confirm that the expression levels of TLR7, TLR9 and constituents of TGF-β signaling, OAZ1 and P-Para were significantly altered in the tumor tissues of Smad3+/− VD-deprived mice compared to the tumor tissues of wild type VD deprived mice tumor tissues." (PMID 27456065, 2016). "The essential role of OAZ1 in inhibiting ODC and polyamine uptake suggests that OAZ1 is a negative regulator of cell proliferation and tumor development." (PMID 28362829, 2017). "In the present study, our results, that HDAC inhibitor S11 inhibited the tumor growth of cisplatin-resistant NSCLC cells and malignant behavior through upregulating OAZ1, prompted us to evaluate the effectiveness of combination therapy as an approach for cisplatin-resistant NSCLC." (PMID 31127087, 2019). "Finally, we validated their expression using qPCR in an additional set of tumor:matched normal samples that resulted in five genes (RPL30, RPL27, PSMC5, MTCH1, and OAZ1), out of which RPL30 and RPL27 were most stable and were abundantly expressed across the tissues." (PMID 30128175, 2018).
infection (3 papers, 2020 to 2022). The state of being infected such as from the introduction of a foreign agent such as serum, vaccine, antigenic substance or organism. "We further showed that the infection of RYSV in leafhopper vector upregulates ODC1 expression but inhibits OAZ1 expression, which would facilitate the conversion of ornithine to PUT." (PMID 37676339, 2022). "In conclusion, based on both expression stability and expression level, our data suggest that Oaz1 is a good reference gene for evaluation and normalization of gene expression in the thymus during ontogeny and after CV-B4 infection." (PMID 32150956, 2020). "Oaz1 expression remained fairly stable from Day 17G to Day 5, even in infected thymuses, with fold changes between 0.5 and 1.7 following infection at Day 10G or 17G, as in mock-infected thymuses." (PMID 32150956, 2020). "For qPCR analysis, we used Oaz1 as an internal control gene, as we recently demonstrated that it is the most stable in the thymus, among other tested housekeeping genes, during development of Swiss albino mice and following their in utero infection by CV-B4." (PMID 34361972, 2021). "However, in this study, we find that the infection of the cytorhabdovirus rice stripe mosaic virus (RSMV) in leafhopper vector could significantly upregulates both OAZ1 and ODC1 expression, which also facilitates the conversion of ornithine to PUT expression." (PMID 37676339, 2022). "For qPCR analysis, we used Oaz1 as an internal control gene, as we recently demonstrated that it is the most stable in the thymus, among other tested housekeeping genes, during the development of Swiss albino mice and following their in utero infection by CV-B4." (PMID 34361972, 2021).
head and neck tumor (1 paper, 2018). "Our data suggest that RPL30 or RPL27 in combination with either PSMC5 or MTCH1 or OAZ1 can be used as a minimal set of control genes in head and neck tumor gene expression studies." (PMID 30128175, 2018).
OAZ1 also shares sentences with these, for which no sentence is quoted: chronic myeloid leukemia (1 paper); colitis (1); gastric cancer (1); Oral leukoplakia (1); parasitic infections (1); testicular tumors (1).